INS (insulin)
Diseases named in the same sentence as INS in open-access papers (continued):
Sharing a sentence is not in itself a finding about the gene and the disease.
metabolic syndrome (continued). "It should also be noted that metabolic syndrome criteria are not effective in identifying insulin resistant individuals, and insulin resistant individuals not identified are also at increased CVD risk." (PMID 35439985, 2022). "Our study illustrated that serum cortisol was associated with dyslipidemia (TC, TG, HDL-C, and LDL-C), impaired glycometabolism (β cell function, FPG, HbA1c, and fasting insulin) but not with SBP and DBP and weight-related indictors (BMI) in T2DM patients." (PMID 35761983, 2022). "Participants with metabolic syndrome were more insulin-resistant and had higher insulin secretion than those without metabolic syndrome." (PMID 36012589, 2022). "For example, in patients with severe obesity and metabolic syndrome, fecal microbial transplantation from lean donors improved insulin sensitivity with no serious adverse effects." (PMID 36551210, 2022). "Baseline characteristics of groups with and without concurrence of metabolic syndrome criteria (MetS) and predicted insulin sensitivity index (ISI-cal)." (PMID 36352897, 2022). "After controlling for additional covariates, such as hypertension, dyslipidemia, smoking, drinking, regular exercise status, BMI, FBS, insulin status, number of anti-diabetic medications, and DM duration, the risk remained higher in the DR group (aHR=1.125, 95% CI:1.108-1.142)." (PMID 35909567, 2022). "As we known, the increased circulating FGF21 levels were positively correlated with metabolic syndrome in obese population, because the physiological increased dose of circulating FGF21 helps to maintain insulin sensitivity in specific tissues during the early stages of these diseases." (PMID 34912302, 2021). "A randomized double-blinded study showed that 7-day Vac treatment reduced peripheral insulin sensitivity in obese males with metabolic syndrome, whereas another study found that it did not affect tissue-specific insulin sensitivity in obese, prediabetic males." (PMID 34222250, 2021). "In a study of patients with metabolic syndrome, heme arginate did not improve endothelial function or insulin sensitivity, but significantly reduced the vasodilatory response to nitroglycerin." (PMID 33670516, 2021). "Increased risk of pancreatic cancer in patients with metabolic syndrome could be due to lower levels of adiponectin (a protein hormone linked to glucose level regulation and fatty acid breakdown), which results in a lack of insulin-sensitizing and anti-inflammatory capabilities." (PMID 34527218, 2021). "Age, WC, insulin, FSH, and SHBG were significant independent predictors for dyslipidemia." (PMID 34977197, 2021). "Though we did not assess blood pressure or insulin sensitivity to determine metabolic syndrome in our study participants, age and BMI were comparable to participants in both of these studies." (PMID 33917165, 2021). "Non-catechin flavonoids from seeds improved TNF-α-impaired insulin, stimulating glucose uptake and insulin signaling with anti-metabolic syndrome and anti-inflammatory properties." (PMID 34054806, 2021). "(e) Fasting acylated/nonacylated ghrelin ratios have been found high in insulin resistant conditions (such as the metabolic syndrome) and low in insulin sensitive conditions." (PMID 33419065, 2021). "The wholegrain diet characterized by low GI, applied for a quite long time (12 weeks) in individuals with metabolic syndrome, also did not affect plasma concentrations of glucose, insulin, and triglycerides measured at fast." (PMID 33810414, 2021). "In summary, the analysis of the insulin-mimetic property of EWH may aid in the effective prophylaxis and management of metabolic syndrome in the future." (PMID 34976961, 2021). "This imbalance between pro- and anti-inflammatory adipokines may lead to impaired insulin sensitivity in adipose tissue, increasing the concentrations of FFA and promoting dyslipidemia." (PMID 34436238, 2021).
metabolic syndrome (continued). "We used prospective data of 608 well-phenotyped Finnish men collected from the population-based Metabolic Syndrome in Men (METSIM) study to build machine learning models for predicting continuous glucose and insulin measures in a shorter (1.5 year) and longer (4 year) period." (PMID 33594006, 2021). "In the other studies serum FABP5 levels correlated positively with parameters of adiposity, adverse lipid profiles, serum insulin, adipocyte fatty acid binding proteins (A-FABP, FABP4), C-reactive protein levels and were higher in subjects with the metabolic syndrome (MS)." (PMID 34131888, 2021). "The current study highlights the potential benefits of pharmacologically increasing PUFAs and decreasing LCAC levels by methyl-GBB to improve insulin sensitivity and mitochondrial functionality as well as the cardioprotective effect of methyl-GBB in treating metabolic syndrome." (PMID 34367467, 2021). "Preliminarily, the obese group in this study was older, had a higher frequency of dyslipidemia and hypertension, and had higher serum glucose and insulin levels than non-obese individuals." (PMID 33924357, 2021). "Negative correlations between muscle mass, muscle strength and metabolic syndrome, independent of insulin resistance and central fat deposition were documented in Australian men aged 38-81 years." (PMID 33640880, 2021). "In this study, butyrate supplementation did not increase butyrate levels either in feces or plasma, but it improved both peripheral and hepatic insulin sensitivity in individuals without metabolic syndrome." (PMID 34737725, 2021). "A recent study in a rabbit model of HFD-induced metabolic syndrome indicated that long-term treatment with INT-767 decreased HFD-induced fatty acid synthesis and fibrosis, while increasing lipid handling and improving insulin resistance." (PMID 32982723, 2020). "Although defects in the insulin signaling pathway have been widely studied, the effects of cellular mechanisms activated during metabolic syndrome that cross-talk with insulin responses are not fully elucidated." (PMID 32977552, 2020). "The fact that consumption of DDW simultaneously influenced the levels of insulin, HDL and glucose suggests that the level of D within the organism may have an important role in harmonizing parameters belonging to metabolic syndrome." (PMID 32197347, 2020). "In obese mice models, a lack of TNF-α resulted in an improvement in insulin sensitivity and glucose homeostasis, confirming that the inflammatory response plays a critical role in the regulation of insulin action in metabolic syndrome." (PMID 32161549, 2020). "Consistent with this, mice bearing a Vav2 protein with decreased catalytic activity exhibit reduced muscle mass, lack of proper insulin responsiveness and, at much later times, a metabolic syndrome-like condition." (PMID 33199701, 2020). "Since insulin suppresses VLDL production, IR knockout predicts dyslipidemia." (PMID 32128655, 2020). "The association between hepatic fibrosis and atherosclerosis progression was significant in all metabolic subgroups regardless of age, body mass index, presence of metabolic syndrome, or insulin sensitivity (all p < 0.05)." (PMID 32534588, 2020). "It demonstrated a systemic effect of the drug with decreased weight gain, improved insulin sensitivity (HOMA-IR, adiponectin), dyslipidemia (triglycerides and cholesterol) along with resolution of steatohepatitis and improvement in all of the key histological features of NASH." (PMID 32518275, 2020). "In particular, we believe that, in addition to the absence of the metabolic syndrome criteria, the degree of insulin sensitivity should be assessed in overweight/obese children and adolescents in order to identify those at low risk." (PMID 32731619, 2020).
metabolic syndrome (continued). "Also, in line with our observation that women display lesser insulin sensitivity improvements than men, the PREVIEW study found that men displayed better improvement of the Metabolic Syndrome status than women (p < 0.001)." (PMID 32514005, 2020). "Interestingly, p-mTOR was higher in patients with metabolic syndrome than those with different etiology, and, similar to SIRT-3, in metformin-treated than insulin-treated patients." (PMID 30917505, 2019). "Adiponectin enhances basal glucose and insulin-stimulated glucose uptake in adipose tissues via AMPK activation and its levels demonstrated an inverse correlation with adiposity and proinflammatory cytokines in patients suffering from metabolic syndrome." (PMID 31261958, 2019). "Physical exercise over 4 weeks followed by 8 weeks of an obesogenic diet slowed weight gain transiently but did not revert the metabolic syndrome and fasted glucose, insulin, triglyceride and total cholesterol remained elevated." (PMID 30850619, 2019). "Raised GC levels, which occur under conditions such as chronic stress, are associated with a range of psychophysical pathologies, including the metabolic syndrome and CVD, via their effect on the liver to enhance glucose, fat accumulation and glucose-dependent insulin insensitivity." (PMID 31146395, 2019). "Our data showed that fructose feeding failed to induce significant dyslipidemia but fasting serum glucose and insulin modestly elevated." (PMID 31307427, 2019). "When dyslipidemia was evaluated, triglyceride values showed a clear elevation in insulin-resistant subjects with respect to noninsulin-resistant controls; however, cholesterol levels did not significantly differ between groups." (PMID 29675435, 2018). "It is in line with present study, since our patients in spite of morbid obesity were insulin sensitive and did not display symptoms of metabolic syndrome." (PMID 29335416, 2018). "Our findings indicate that diet-induced diastolic changes occur in animals showing resistance to metabolic syndrome and T2DM, independently of body weight (males had similar fasting insulin and blood glucose levels as well as body weight in both dietary groups studied here)." (PMID 30589871, 2018). "The progression toward metabolic syndrome, characterized by reduced glucose clearance and insulin sensitivity, does not alter body mass until multiple days of exposure to SF." (PMID 29479505, 2018). "Some data suggested that in 32 years old men with metabolic syndrome (MetS), P1NP, together with OC resulted lower compared to healthy men, and inversely correlated with insulin and glucose, although these relationships lost significance in a fully adjusted model." (PMID 29914099, 2018). "Although we did not measure insulin levels, reduction in serum insulin has been reported following administration of empagliflozin for 7 weeks in a metabolic syndrome model rat." (PMID 30049285, 2018). "The decrease in metabolic syndrome prevalence was not correlated with a reduction in insulin dose requirement (r = 0.45, p = 0.23)." (PMID 29338714, 2018). "Our study supports the insulin sensitizing activity of SSE and suggests that this extract might improve other manifestations of the metabolic syndrome." (PMID 29768504, 2018). "In summary, the mice fed a HF/HS diet post-weaning had several features of metabolic syndrome including increased weight gain, impaired glucose tolerance, increased fat, and elevated cholesterol and serum insulin regardless of maternal diet." (PMID 29775456, 2018). "Obese individuals have reduced insulin sensitivity leading to hyperinsulinemia and eventually dyslipidemia with nontreatment of these conditions increasing obese individuals' susceptibility for developing a diabetic phenotype with an increased risk for CVD." (PMID 29484207, 2018).
metabolic syndrome (continued). "The PPARG gene, located at 3p25-24, and plays a non-ignorable role in adipocytes differentiation, insulin sensitivity regulation, and its variation has been reported association with some CAD related risk factors, such as T2DM or metabolic syndrome (MS)." (PMID 28415751, 2017). "The present study data also indicates that circulating ZAG correlates positively with age, HDL-C, and HOMA-β and negatively with parameters of adiposity (WHR, FAT% and BMI), IR (increased fasting insulin and HOMA-IR), dyslipidemia (increased TG and FFA), DBP, and SBP." (PMID 28814962, 2017). "Higher-volume high intensity training (HIIT) with 4 × 4 min per session elicited greater improvements than 1 × 4 min of HIIT, or moderate intensity training, in insulin quality in metabolic syndrome (MetS) participants without type 2 diabetes." (PMID 28292300, 2017). "Subjects with dyslipidemia and NGT have impaired insulin sensitivity and β cell function." (PMID 28199386, 2017). "The dyslipidemia that was observed in HFD‐fed hamsters improved with IMM‐H007 treatment without affecting food consumption, as evidenced by reduced serum levels of TGs, cholesterol, and FFAs, together with decreased levels of plasma insulin and transaminases." (PMID 28904866, 2017). "The authors found no improvement in insulin sensitivity, but 18 subjects had the metabolic syndrome and the mean BMI for all 23 patients was 32 kg/m2, compared to only 29 kg/m2 in our study." (PMID 29082259, 2017). "Intra-adipose cortisol was positively associated with fasting insulin but not with 11β-HSD1, suggesting that higher adipose 11β-HSD1 activity is associated with features of the metabolic syndrome." (PMID 28824543, 2017). "CPAP therapy alone did not have a significant effect on inflammation, insulin sensitivity, or dyslipidemia, even among participants who adhered to the therapy." (PMID 27314230, 2016). "With complete penetrance, 12-week-old Mmp11−/−mice displayed significantly increased serum glucose, insulin, total cholesterol, triglycerides (TG) and, FFA levels, together with hyperleptinemia and hypoadiponectinemia, suggestive of a metabolic syndrome phenotype." (PMID 27126782, 2016). "Insulin treatment only reduced FFA levels, while the dyslipidemia remains present." (PMID 27119007, 2016). "Pharmaceutical compounds that activate peroxisome proliferator-activated receptor (PPAR)-α and PPAR-γ (e.g., fibrates and thiazolidinedione, respectively) have been successful as potent lipid-lowering and insulin-sensitizing therapies for CVD and diabetes-related dyslipidemia." (PMID 27777929, 2016). "Repeating the analyses after categorizing individuals based on their paternal country of birth did not change our findings, except for dyslipidemia and insulin dosage." (PMID 26295472, 2015). "Many of the body composition measurements such as weight, waist, hip, waist to hip ratio were strongly correlated with blood pressure, cholesterol levels, insulin and glucose measurements and inversely correlated with HDL levels, defining the metabolic syndrome." (PMID 25853885, 2015). "This enzyme also appears to be involved in the etiology of metabolic syndromes because its suppression results in decreased fat deposits (regardless of food intake), improved insulin sensitivity and higher basal energy expenditure." (PMID 26046927, 2015). "Decreased insulin sensitivity following a one-week antibiotic course with vancomycin was reported in obese males with metabolic syndrome, whereas no change in insulin sensitivity was observed following administration of amoxicillin for one week." (PMID 26562532, 2015). "However, even though the DIO rat is a popular model for the metabolic syndrome the DIO rat only reflects the obese and insulin resistant phenotypes." (PMID 26266945, 2015). "Prevalence of various metabolic syndrome criteria increased among participants without metabolic syndrome who had even only mild insulin elevation." (PMID 26241903, 2015).
metabolic syndrome (continued). "The HMW oligomer forms of adiponectin have recently been shown to possess the greatest insulin-sensitizing activity, and the ratio of HMW to total adiponectin has been reported to be more useful for predicting IR and the metabolic syndrome than the total adiponectin level." (PMID 26039731, 2015). "Fasting insulin concentrations did not change either (metabolic syndrome post training 128 ± 28 pmol/L; controls post training 31 ± 4 pmol/L)." (PMID 25472611, 2014). "The lack of hepatic steatosis in the treated rats was an unexpected finding; therefore, we did not control for insulin or other markers of metabolic syndrome, such as lipid profile (i.e. HDL cholesterol, triglycerides, remnant lipoproteins, etc.)and/or ROS." (PMID 24799459, 2014). "In a recent non-interventional study examining 80 patients with metabolic syndrome, it was reported that an increase of one unit in insulin levels resulted in a decrease of 0.25 units in SHBG levels." (PMID 24714992, 2014). "Although metabolic syndrome as defined by IDF standards was considered an exclusion criterion, individuals in the lower HDL size tertile had higher triglycerides levels, waist circumference and lower insulin sensitivity than their counterparts." (PMID 25470778, 2014). "Because insulin is a potent inhibitor of SHBG production in the liver, it is possible that decreased levels of SHBG could be an early marker for metabolic syndrome." (PMID 24714992, 2014). "Patients in the first tertile showed significantly lower levels of fasting insulin, HbA1c, fasting and postprandial triglycerides and in accordance to this the fraction of patients with T2DM or metabolic syndrome in the first tertile was considerably lower in comparison to the other tertiles." (PMID 25408147, 2014). "Most recently our own data has shown restored first-phase insulin secretion in metabolic syndrome; however, the lack of translational work has recently been highlighted." (PMID 24671124, 2014). "Similarly, the obese PCOS had high BMI, waist to hip ratio (WHR), fasting glucose, LH, LH/FSH, fasting insulin, HOMA score (IR), and dyslipidemia, compared with lean PCOS and controls." (PMID 24696694, 2014). "Face-to-face interview data such as smoking, drinking, DM family history, hypertension, metabolism syndrome, and treatment with insulin were compared between GERD and non-GERD groups." (PMID 25530757, 2014). "Presence of metabolic syndrome, CIMT and baseline variables (fasting glucose, lipids, insulin, cardiovascular disease-related measurements, CD4+ T cell counts and HIV RNA levels, high-sensitivity C-reactive protein, serum sCD14, serum LPS) have previously been determined." (PMID 23510548, 2013). "Whereas insulin was released within minutes of a meal, FGF19 serum levels peaked 2 h after a meal, and, accordingly, circulating FGF19 levels in humans inversely correlated with fasting glucose levels and metabolic syndrome." (PMID 24260557, 2013). "The frequency of soup consumption was inversely associated with covariate-adjusted body mass index and waist circumference (P<0.05), but not with biomarkers of metabolic syndrome, except for a lower fasting insulin level in frequent soup consumers (P = 0.022)." (PMID 24098709, 2013). "All other measurements, such as height, weight, blood pressure, fasting glucose level, fasting insulin level, and additional measurements relating to the metabolic syndrome, did not exhibit any significant effects concerning the serum MFAP4 level." (PMID 24324779, 2013). "However, as a member of metabolic syndrome (MetS), uric acid (UA) could worsen insulin resistance by disturbing insulin-stimulated glucose uptake." (PMID 24205159, 2013). "The adiponectin concentration is a potent anti-inflammatory adipokine and acts in the regulation of insulin homeostasis, favouring the control of many chronic diseases, including atherosclerosis, hypertension, NAFLD, metabolic syndrome, cardiovascular diseases, thrombosis, and asthma." (PMID 24285955, 2013).